APOA2 (apolipoprotein A2)
Description:
May stabilize HDL (high density lipoprotein) structure by its association with lipids, and affect the HDL metabolism.
Synonyms: Apo-AII; ApoA-II; APOA2D; apoAII
Tractability: Small molecule: it has a binding pocket of medium quality. Antibody: UniProt places it where antibodies can reach, with high confidence; its Gene Ontology location is reachable by antibodies, with high confidence; UniProt predicts a signal peptide or a membrane-spanning region. PROTAC: its protein half-life has been measured.
Gene: Protein-coding gene on chromosome 1 (161,222,290 to 161,224,305, reverse strand). Ensembl gene ENSG00000158874.
Subcellular location: Secreted
Pathways (Reactome):
Metabolism of proteins: Post-translational protein phosphorylation; Regulation of Insulin-like Growth Factor (IGF) transport and uptake by Insulin-like Growth Factor Binding Proteins (IGFBPs)
Transport of small molecules: Chylomicron assembly; Chylomicron remodeling
Metabolism: PPARA activates gene expression
Sensory Perception: Retinoid metabolism and transport
Gene Ontology:
Molecular function: apolipoprotein receptor binding; cholesterol binding; cholesterol transfer activity; enzyme binding; heat shock protein binding; high-density lipoprotein particle receptor binding; lipase inhibitor activity; lipid binding; lipid transporter activity; phosphatidylcholine binding; phosphatidylcholine-sterol O-acyltransferase activator activity; phospholipid binding; protein binding; protein heterodimerization activity; protein homodimerization activity; receptor ligand activity; signaling receptor binding; high-density lipoprotein particle binding
Biological process: cellular response to lipoprotein particle stimulus; cholesterol efflux; cholesterol homeostasis; diacylglycerol catabolic process; high-density lipoprotein particle assembly; high-density lipoprotein particle clearance; high-density lipoprotein particle remodeling; low-density lipoprotein particle remodeling; negative regulation of cholesterol import; negative regulation of cholesterol transport; negative regulation of cytokine production involved in immune response; negative regulation of lipid catabolic process; negative regulation of very-low-density lipoprotein particle remodeling; peptidyl-methionine modification; phosphatidylcholine biosynthetic process; phospholipid catabolic process; phospholipid efflux; positive regulation of interleukin-8 production; positive regulation of lipid catabolic process; positive regulation of phagocytosis; protein oxidation; protein stabilization; regulation of protein stability; response to glucose; reverse cholesterol transport; and 6 more
Cellular component: blood microparticle; chylomicron; extracellular exosome; extracellular region; high-density lipoprotein particle; spherical high-density lipoprotein particle; very-low-density lipoprotein particle; cytosol; early endosome; endoplasmic reticulum lumen
Genetic constraint (gnomAD): Loss-of-function variants: 3 observed, 7.66 expected, observed/expected ratio (o/e) 0.39, 90% interval 0.18 to 1.01. That is too few expected variants to judge how well the gene tolerates losing a copy. Missense variants: 88 observed, 118.66 expected, observed/expected ratio (o/e) 0.74, 90% interval 0.62 to 0.88. Synonymous variants: 42 observed, 49.8 expected, observed/expected ratio (o/e) 0.84, 90% interval 0.66 to 1.09.
Homologues: Orthologues: chimpanzee APOA2 (97% identical), macaque APOA2 (93% identical), dog APOA2 (80% identical), rabbit APOA2 (76% identical), pig APOA2 (73% identical), guinea pig APOA2 (66% identical), mouse Apoa2 (63% identical), rat Apoa2 (56% identical).
Diseases named in the same sentence as APOA2 in open-access papers:
APOA2 is named in the same sentence as 159 diseases in open-access papers, as found by Europe PMC text mining. Sharing a sentence is not in itself a finding about the gene and the disease. The quoted sentences say what the papers report.
atherosclerosis (35 papers, 2007 to 2025). A disease characterized by the build-up of fatty material and calcium deposition in the arterial wall resulting in partial or complete occlusion of the arterial lumen. "Qrr1 also shows strong concordance with the orthologous human Chr1 q21–q23 interval, which harbors genes such as Rgs2 (anxiety), Apoa2 (atherosclerosis), and Kcnj10 (seizure susceptibility)." (PMID 41225772, 2025). "APOA1 or APOA2 deficiency can cause hypertriglyceridemia and in the long-term atherosclerosis." (PMID 36189295, 2022). "The polymorphism of Apoa2 is related to lipid metabolism, obesity and atherosclerosis in human." (PMID 32733872, 2020). "Some research has found a link between residual atherosclerosis and Apoa2, whereas others have found Apoa2 to be an atherogenic factor." (PMID 36242090, 2022). "Furthermore, HDL-C is a highly heterogeneous class of lipoproteins, the main members of which are ApoA1 and ApoA2, which have major antioxidant and anti-inflammatory properties that effectively prevent atherosclerosis." (PMID 38155948, 2023). "In addition, knock-in of human ApoA2 in rabbits reduced atherosclerosis, in line with our observation of a hepatic key regulator being down-regulated on the high-fat diet." (PMID 35897797, 2022). "In human, increasing APOA2 synthesis decreases the incidence of atherosclerosis." (PMID 32733872, 2020). "APOA2 also play different roles in human and mice atherosclerosis." (PMID 32733872, 2020). "The link between Apoa2 and atherosclerosis, on the other hand, remains unclear." (PMID 36242090, 2022). "ApoA2 may serve as a potential therapeutic target for atherosclerosis." (PMID 35845789, 2022). "Study showed that expressing APOA2 and APOA1 are more vulnerable to suffering from atherosclerosis than those expressing APOA1 alone in mice." (PMID 38177949, 2024). "Indeed, the key genes enriched in the cholesterol binding pathway have links to cholesterol efflux (ABCG1), inflammation, and atherosclerosis (ABCB1 and APOA2)." (PMID 24763700, 2014).
Obesity (34 papers, 2010 to 2025). Accumulation of substantial excess body fat. "One of the SNPs associated with anthropometric indices, obesity, and inflammatory markers is the APOA2 (rs5082)." (PMID 40597178, 2025). "Findings suggested a strong relationship between APOA2–265 T > C polymorphism and leptin and ghrelin levels as an effective possible mechanism for obesity which reported a high serum ghrelin among CC patients." (PMID 35883173, 2022). "APOA2–265 T > C polymorphism (rs5082) is one of the single nucleotide polymorphisms (SNPs) which is related to anthropometric indices, obesity, insulin resistance, and plasma lipids level." (PMID 35883173, 2022). "The maternal effect seen on ApoA2 would be expected to be negatively associated with cardiovascular, while the effect on obesity would be expected to be beneficial." (PMID 35052431, 2021). "Eating behaviours have been identified as related to obesity risk and appear to be associated with APOA2 genotype in a manner consistent with obesity risk." (PMID 24382995, 2013). "Homozygous individuals for the C allele had higher body mass index (BMI) and obesity risk than the carriers of the T allele, but relationships between APOA2 c.-492T>C genotype and obesity among Egyptian adolescents are unexplored till now." (PMID 24382995, 2013). "Association between APOA2 c.-492T>C SNP and BMI or obesity only in the presence of high-saturated fat intake in three American populations has been observed." (PMID 24382995, 2013). "The present study found strong association between the APOA2 c.-492T>C SNP polymorphism and obesity risk and anthropometric measures." (PMID 24382995, 2013). "Through transgenic and knockout studies it has been shown that Apoa2 is involved in controlling plasma cholesterol and triglyceride levels and over-expression causes insulin resistance and obesity." (PMID 21167066, 2010). "APOA2 is one of the key genes associated with an increased risk of obesity, T2DM, and CVDs." (PMID 40597178, 2025). "Certain polymorphisms of Apoa2 are known to be associated with obesity." (PMID 36834799, 2023). "Studies proposed that these subjects had up-regulated methylation at cg04436964, close to ApoA2 gene, versus T carriers which linked with down-regulated ApoA2 expression that might be a justification for obesity trait by gene-diet interaction." (PMID 35883173, 2022). "Previous studies have revealed that APOA1 and APOA2 genes were key regulatory factors of high density lipoprotein metabolism, which is significantly associated with obesity and body weight in humans; APOA1 and APOA2 have been considered as candidate genes for back fat thickness in pigs." (PMID 31009469, 2019). "Similarly, a variant of the APOA2 gene increases the association with obesity in those consuming high levels of saturated fatty acids." (PMID 28690685, 2017). "Therefore, our objectives were to analyzing the association between the APOA2 c.-492T>C polymorphism SNP and the risk of obesity and study its association with anthropometric measurements, body fat distribution, food consumption, and lipid metabolism in a sample of Egyptian adolescents." (PMID 24382995, 2013). "Moreover, other study reported genotype-associated differences in specific intake-related behaviours, which may contribute to obesity risk, identifying the possible role of ghrelin in modulating APOA2-nutrient interactions." (PMID 24382995, 2013). "As a major component of high-density lipoprotein, APOA2 plays a critical role in lipid metabolism and obesity-related pathways." (PMID 40507856, 2025). "APOA2 was one of the main apolipoproteins of high density lipoprotein, which played a key role in lipid metabolism and obesity." (PMID 36192674, 2022). "One of the main genes involved in increased risk of obesity, T2DM, and CVDs is apolipoprotein A2 (ApoA2)." (PMID 35883173, 2022).
Obesity (continued). "For instance, a recent study of the mechanism by which APOA2-saturated fat intake affects obesity was validated across several populations in an epigenome-wide association study." (PMID 32485899, 2020). "More recent studies of the APOA2 gene clarified the role of the APOA2 protein in regulating adiposity and body weight by demonstrating that the APOA2 gene interacts with a high-fat diet to promote weight gain and obesity." (PMID 22043166, 2011). "An interaction between the Apolipoprotein A-II (APOA2) -265T>C SNP and high-saturated fat in relation to BMI and obesity has been reported in five independent populations." (PMID 22043165, 2011). "APOM, APOA2, APOC3, and APOA1, all apolipoproteins, were associated with lipid transport and involved in the PPAR signaling pathway and cholesterol metabolism, which played important roles in obesity development." (PMID 40438591, 2025). "This diet-dependent outcome related to obesity may be explained by the methylation status of the CC APOA2 promoter, which leads to reduced APOA2 expression in people consuming a high-SFA diet." (PMID 38281958, 2024). "Thus, our results demonstrate that CETP and APOA2 SNPs can be suggested as key elements for genotype-based precision medicine for obesity." (PMID 38062157, 2023). "Obesity increased Apoa2 expression in the current study, and it decreased following the empagliflozin intervention, but more research is needed to evaluate whether empagliflozin has cardioprotective effects by changing Apoa2 expression." (PMID 36242090, 2022). "Empagliflozin may protect the heart by altering the expression of genes including Apoe, Apoc1, Saa2, Apoa2, and Pon1, which are all involved in lipid metabolism disturbance in obesity." (PMID 36242090, 2022). "APOA2 is related to obesity, dyslipidemia and lipid metabolism." (PMID 34090334, 2021). "The role of APOA2 in obesity could be explained by promoting and inhibiting cholesterol efflux controlled by the enzymatic activity." (PMID 32120838, 2020). "Considering the effect of the obesity and genetic basis of the APOA2 rs3813627 SNP on HDL levels, we hypothesized that the genotype risk of this polymorphism could be associated with anthropometrical variables, glucose metabolism, and lipid traits." (PMID 32120838, 2020). "For example, apolipoprotein A2 (ApoA2) was one of the top obesity-regulated proteins." (PMID 32411709, 2020). "Both APOA2 and APOA5 were linked to increased risk of obesity and metabolic syndrome." (PMID 31831817, 2019). "Overall, a number of interesting genes that could play a role in obesity susceptibility have been identified within these CNVs (e.g. ASTN2, APOA2, PARK2, LINGO2, PLCB1, PTEN, and CIDEA)." (PMID 29441128, 2018). "The aim of this study was to determine the interaction of dietary fat intake with the APOA2 (rs3813627 and rs5082), APOA5 (rs662799 and rs3135506) and LEPR (rs8179183 and rs1137101) polymorphisms and its relationship with obesity and dyslipidemia in young subjects." (PMID 26365669, 2015). "The objective of this study was to analyze the interaction of a high fat diet with the APOA2 (rs3813627 and rs5082), APOA5 (rs662799 and rs3135506) and LEPR (rs8179183 and rs1137101) polymorphisms and its relationship with obesity and dyslipidemia in young subjects." (PMID 26365669, 2015). "Further examination of DEPs revealed that following empagliflozin treatment, the expressions of Apoe, Apoc1, Saa2, Apoa2, and Pon1 altered dramatically, suggesting that these proteins may be the main proteins that empagliflozin uses to treat obesity-induced aberrant lipid metabolism." (PMID 36242090, 2022). "The findings on the interplay effect of ApoA2–265 T > C and DAL on obesity markers were in line with various studies." (PMID 35883173, 2022). "However, recent studies have shown that APOA2 plays multiple roles in the maintenance of HDL, obesity, and obesity-related insulin resistance." (PMID 32120838, 2020).
Obesity (continued). "APOA2, the second most abundant constituent of HDL, plays an important role in lipid transport and metabolism including visceral fat accumulation and metabolism of triglyceride-rich lipoproteins, and has been related to obesity." (PMID 31349543, 2019). "APOA2 CC homozygotes at − 265 T > C are at increased risk of obesity when consuming a diet high in SFA compared with TT carriers, but they have no increased risk of obesity when consuming a low-SFA diet." (PMID 38281958, 2024).
pancreatic cancer (34 papers, 2010 to 2026). "The multivariate analysis revealed pancreatic cancer to be an independent risk factor for APOA2-i Index positivity (odds ratio [OR]: 3.48, p < 0.001), CA 19-9 positivity (OR: 25.5, p < 0.001), and positivity for either marker (OR: 13.3, p < 0.001)." (PMID 40227633, 2025). "This study evaluated the diagnostic effectiveness of the Apolipoprotein A2-isoform (APOA2-i) Index for early detection of pancreatic cancer in combination with the conventional tumor marker CA 19-9." (PMID 40227633, 2025). "The combination of both biomarkers showed improved diagnostic accuracy for early-stage pancreatic cancer, highlighting the potential of APOA2-i as a valuable tool in clinical settings." (PMID 40227633, 2025). "This study aimed to evaluate the diagnostic performance of the APOA2-isoform (APOA2-i) Index in patients with pancreatic cancer." (PMID 40227633, 2025). "APOA2 has also been linked to cancer and has potential diagnostic and prognostic value in pancreatic cancer, lung cancer, prostatic cancer, colorectal cancer, metastatic renal cancer, and gastric cancer." (PMID 38136890, 2023). "ApoA2 isoforms are a potential biomarker for detecting patients with pancreatic cancer and the risk diseases of PDAC." (PMID 27673558, 2016). "This biomarker can distinguish patients with stage I/II of pancreatic cancer and its risk diseases from healthy subjects by detection of the cleaved pattern of the C-terminal ends of the amino acids of the apolipoprotein A2 (apoA2) homodimer." (PMID 27673558, 2016). "In addition, we describe the potential clinical usefulness of apoA2 isoforms for the detection of pancreatic cancer and its risk diseases." (PMID 27673558, 2016). "We recently identified a unique alteration in apolipoprotein A2 isoforms in pancreatic cancer and its precancerous lesions, and we describe its clinical usefulness as a potential biomarker for the early detection and risk stratification of pancreatic cancer." (PMID 27673558, 2016). "Recently, apolipoprotein A2 isoforms (ApoA2-ATQ/AT) have been reported as a new blood biomarker for pancreatic cancer." (PMID 41976399, 2026). "Another biomarker of pancreatic cancer is apolipoprotein A2 (apoA2), which has been reported to have a characteristic processing pattern in pancreatic cancer patients." (PMID 40895517, 2026). "The study of APOA2 mainly focused on hepatocellular carcinoma, prostate cancer, gastric cancer, myeloma, and pancreatic cancer, however, the importance of APOA2 on obstetrics and gynecology was reported recently." (PMID 38177949, 2024). "In pancreatic cancer, APOA2, APOC1, APOC2, and APOJ have been described, while APOB was found in HCC, bladder, and breast cancer." (PMID 37628784, 2023). "Patients with pancreatic cancer were found to have a decrease in the plasma concentration of a specific isoform of APOA2 called APOA2-ATQ/-AT." (PMID 38067270, 2023). "Apolipoprotein A-II (APOA2) was identified as a minimally invasive biomarker for detecting pancreatic cancer, lung cancer and renal cell cancer." (PMID 35371990, 2022). "Compared to CA19-9 alone, a combination of CA19-9 and ApoA2-ATQ/AT detects pancreatic cancer up to 18 months earlier than the traditional methods." (PMID 34907282, 2021). "We previously reported that circulating apolipoprotein A2 undergoes unique processing in the bloodstream of patients with pancreatic cancer and its precancerous lesions." (PMID 32707720, 2020). "The AUC values for CA19-9 and apoA2-ATQ/AT isoform as single biomarkers to distinguish patients with early stage pancreatic cancer (stage I/II) were 0.783 (95% CI 0.64, 0.95, 0.699–0.855), and 0.809 (95% CI, 0.748–0.867), respectively." (PMID 32707720, 2020). "The AUC value of apoA2-ATQ/AT in pancreatic cancer to distinguish patients with PDAC from healthy controls was 0.876." (PMID 27673558, 2016).